DBF4 (DBF4-CDC7 kinase regulatory subunit)
Description:
Regulatory subunit for CDC7 which activates its kinase activity thereby playing a central role in DNA replication and cell proliferation. Required for progression of S phase. The complex CDC7-DBF4A selectively phosphorylates MCM2 subunit at 'Ser-40' and 'Ser-53' and then is involved in regulating the initiation of DNA replication during cell cycle.
Synonyms: ASK; DBF4A; ZDBF1; chif
Tractability: Small molecule: a structure with a bound ligand is known; a high-quality ligand is known; it belongs to a druggable protein family. PROTAC: ubiquitination databases record sites on it.
Target class: Kinase; Protein kinase regulatory subunit; Enzyme
Chemical probes: PD082077, PD083009, PD083960, PD084012, PD134131, PD134132, PD134135, PD134136, PD134137, PD134138
Gene: Protein-coding gene on chromosome 7 (87,876,216 to 87,909,553, forward strand). Ensembl gene ENSG00000006634.
Subcellular location: Nucleus
Subcellular location (Human Protein Atlas): Nuclear bodies; Nucleoplasm
Pathways (Reactome):
Cell Cycle: Activation of ATR in response to replication stress
DNA Replication: Activation of the pre-replicative complex
Gene Ontology:
Molecular function: protein binding; enzyme activator activity; protein serine/threonine kinase activator activity; nucleic acid binding; zinc ion binding
Biological process: DNA replication; G1/S transition of mitotic cell cycle; mitotic DNA replication checkpoint signaling; mitotic intra-S DNA damage checkpoint signaling; positive regulation of nuclear cell cycle DNA replication; regulation of cell cycle phase transition
Cellular component: Dbf4-dependent protein kinase complex; nuclear body; nucleoplasm; nucleus
Genetic constraint (gnomAD): Loss-of-function variants: 19 observed, 58.65 expected, observed/expected ratio (o/e) 0.32, 90% interval 0.22 to 0.47. The upper end of that interval is the gene's LOEUF score, 0.47, which puts it in group 2 of 6, group 1 being the genes least tolerant of losing a copy. Missense variants: 562 observed, 675.37 expected, observed/expected ratio (o/e) 0.83, 90% interval 0.78 to 0.89. Synonymous variants: 195 observed, 232.12 expected, observed/expected ratio (o/e) 0.84, 90% interval 0.75 to 0.95.
Homologues: Orthologues: chimpanzee DBF4 (99% identical), chimpanzee DBF4 (96% identical), pig DBF4 (83% identical), dog DBF4 (83% identical), guinea pig DBF4 (78% identical), rat Dbf4 (68% identical), mouse Dbf4 (67% identical), tropical clawed frog dbf4 (31% identical), zebrafish dbf4 (25% identical), Drosophila melanogaster chif (19% identical). Paralogues in human: DBF4B (19% identical).
Diseases named in the same sentence as DBF4 in open-access papers:
DBF4 is named in the same sentence as 21 diseases in open-access papers, as found by Europe PMC text mining. Sharing a sentence is not in itself a finding about the gene and the disease. The quoted sentences say what the papers report.
breast carcinoma (5 papers, 2009 to 2022). "We screened a panel of 15 breast cancer cell lines for Cdc7 and Dbf4 expression using monoclonal antibodies against each subunit." (PMID 25412417, 2014).
melanoma (3 papers, 2020 to 2024). A malignant, usually aggressive tumor composed of atypical, neoplastic melanocytes. "More than 10 years ago, some scholars pointed out that higher ASK/Dbf4-expressing melanomas were associated with lower relapse-free survival." (PMID 34975331, 2022).
central nervous system cancer (2 papers, 2023 to 2024). "The results showed that the expression of DBF4 was significantly up-regulated in liver cancer, brain and central nervous system cancer, head and neck cancer and other cancers." (PMID 38724606, 2024). "Overall, the expression of LIN9, MCM8, CEP72, POLA1, DBF4, NDE1 and CDKN2C increase the prognostic risk for patients with glioma." (PMID 37349788, 2023). "The correlation between E2F4 and LIN9, MCM8, CEP72, POLA1, DBF4, NDE1 or CDKN2C expression in glioma tissues was analyzed using CGGA." (PMID 37349788, 2023). "In recurrent gliomas, E2F4 showed a significant positive correlation with the expression of MCM8, DBF4 and CDKN2C." (PMID 37349788, 2023). "There was a strong positive correlation between E2F4 expression and the expression of MCM8, DBF4 and CDKN2C in both primary and recurrent glioma tissues, with the most prominent impact on patient prognosis being observed for MCM8." (PMID 37349788, 2023). "Our analysis revealed a significant positive correlation between E2F4 and MCM8, POLA1, DBF4, NDE1 or CDKN2C expression in primary gliomas." (PMID 37349788, 2023). "The expression of MCM8, DBF4 and CDKN2C displayed a significant positive correlation with E2F4 expression in both primary and recurrent glioma tissues." (PMID 37349788, 2023).
cervical cancer (2 papers, 2017). A primary or metastatic malignant neoplasm involving the cervix. "DBF4 has not been described to be associated with cervical cancer." (PMID 29312619, 2017).
liver cancer (2 papers, 2023 to 2024). An epithelial or non-epithelial malignant neoplasm that arises from the liver. "These experimental findings provide evidence that DBF4 can promote the progression of liver cancer by activating the ERBB signaling pathway and its downstream cascades." (PMID 38724606, 2024). "Subsequent to knocking out DBF4, there was a noticeable decrease in the proliferation, migration, and invasive activity of liver cancer cells." (PMID 38724606, 2024). "In summary, the activation of the ERBB pathway through DBF4 has been shown to enhance the proliferation, migration, and invasion capabilities of liver cancer cells, thereby promoting tumor progression." (PMID 38724606, 2024). "Conversely, overexpression of DBF4 resulted in a significant enhancement in the proliferation, migration, and invasive capabilities of liver cancer cells." (PMID 38724606, 2024). "To confirm the impact of DBF4 on liver cancer cells through the ERBB signaling pathway, we introduced the ERBB inhibitor dacomitinib after DBF4 overexpression." (PMID 38724606, 2024).
ovarian carcinoma (2 papers, 2019 to 2020). A malignant neoplasm originating from the surface ovarian epithelium. "To further compare our results to existing biological knowledge, we found evidence in the literature that CDC7, ORC6L, and DBF4 are associated specifically with ovarian cancer." (PMID 31060502, 2019). "DBF4 encodes for a protein that activates the kinase activity of CDC7 and was found to be associated with ovarian cancer." (PMID 31060502, 2019).
gastric cancer (1 paper, 2021). A primary or metastatic malignant neoplasm involving the stomach. "Silencing of DBF4 repressed the migration of both gastric cancer cells." (PMID 34758839, 2021). "In conclusion, the lactate-miR-30a-DBF4 axis was a critical regulator of GC cell proliferation, migration, sensitivity to 5-Fu and may have potential to serve as a target for the treatment of gastric cancer." (PMID 34758839, 2021). "Gastric cancer cell line MGC-803 and AGS were transfected with DBF4 siRNA or overexpression vector to detect the function of DBF4 in proliferation, migration and the sensitivity to 5-Fu with CCK-8 assay, colony formation assay, transwell assay, and wound healing assay." (PMID 34758839, 2021).
hepatocellular carcinoma (1 paper, 2024). A malignant tumor that arises from hepatocytes. "In this study, our investigation encompassed the impact of DBF4 on hepatocellular carcinoma (HCC) progression and delved into the potential mechanisms." (PMID 38724606, 2024).
lung carcinoma (1 paper, 2015). "Barkley proposed that miR-29a targets the 3-UTR of DBF4 mRNA in lung cancer cells and Bonte stated that most cell lines with increased Cdc7 protein levels also had increased DBF4 abundance, and some tumor cell lines had extra copies of the DBF4 gene." (PMID 25866773, 2015).
lung squamous cell carcinoma (1 paper, 2024). "miR-30d-5p inhibits the proliferation, migration, and invasion of lung squamous cell carcinoma by targeting DBF4." (PMID 39493373, 2024).
cancer (19 papers, 2014 to 2025). A tumor composed of atypical neoplastic, often pleomorphic cells that invade other tissues. "As a proof-of-concept, miRTARGET identified CDC7 and its regulatory unit DBF4 as the top cancer-associated predicted targets of the tumor suppressive miRNA miR-30a." (PMID 40561849, 2025). "According to Kaplan Meier analysis, setting the median expression of DBF4 as a threshold, our study found that high levels of DBF4 expression are associated with adverse survival outcomes in several cancers, including LIHC, ACC, KIRC, KIRP, LGG, etc.." (PMID 38724606, 2024). "Overall, our analysis across pan-cancer revealed that DBF4 is overexpressed in the majority of cancer types, and is associated with unfavorable prognosis, especially notable in HCC." (PMID 38724606, 2024). "Moreover, the overexpression of DBF4 is associated with poor prognosis and various malignant tumors, including HCC, making it a potential independent prognostic indicator in HCC." (PMID 38724606, 2024). "This speculation was further confirmed by pearson and GSEA analysis, the genes highly associated with CDC7 and DBF4 are enriched in cell cycle, DNA replication and microRNA in cancer pathways." (PMID 36609254, 2023). "Additionally, upregulation of DBF4 is associated with lower relapse-free survival in many cancers, indicating that enhanced DBF4 may be a signal of malignancy in humans." (PMID 34758839, 2021). "While our study has investigated the role of DBF4 in various malignant tumors, there are still some limitations." (PMID 38724606, 2024). "In order to gain a deeper understanding of the potential mechanisms by which DBF4 promotes cancer progression, we conducted cellular transcriptomic and KEGG enrichment analyses." (PMID 38724606, 2024). "As a whole complex member and elevated in most cancer types, DBF4 and CDC7 were found positively correlated with each other in 26 TCGA cancer types, especially in HCC." (PMID 36609254, 2023). "Both DDK subunits, Cdc7 and Dbf4, are frequently found to be overexpressed in cancer and this is correlated with cancer development and poor prognosis." (PMID 35614055, 2022). "Although the real interaction between dimers and DBF4 needs further research, our research provided theoretical basis for identifying targets of carboline in treating cancer." (PMID 36325324, 2022). "DBF4 is reported to be scarcely expressed in normal tissues but significantly overexpressed in many cancer cells." (PMID 34758839, 2021). "Both Drf1 and Dbf4 orthologs exist in humans, and Cdc7 kinase is emerging as a potential target in certain cancers." (PMID 28697335, 2017). "The first eight of the nineteen targets, PIAS3, p27, RAB10, DBF4, DUSP14, RBPMS, PDPN and CLTC, were considered to be closely associated with cancer progression after a literature review." (PMID 28120918, 2017). "The oncogenic role of DBF4 in specific cancers is garnering increasing attention in research." (PMID 38724606, 2024). "As DDK is an obvious target for cancer therapy, information about the unique features of Dbf4 in regulating Cdc7 activities provides the necessary details for developing novel anti-cancer drugs that selectively kill cancer cells with low toxic off-target side effects." (PMID 35296675, 2022). "Furthermore, our results suggested that DBF4 also play an important role in the regulation of cancer cells migration." (PMID 34758839, 2021). "Cdc7 and Dbf4 are overexpressed in many types of cancer including oral cancer." (PMID 29209046, 2017). "Therefore, targeting DBF4 interference holds promise as a therapeutic strategy for cancer patients." (PMID 38724606, 2024). "Inhibition of DBF4 has been shown to suppress the migration and adhesion of prostate (PC3), breast (MB231), and cervical (HeLa) cancer cells, thereby impeding metastasis." (PMID 38724606, 2024).
cancer (continued). "Studies have shown that Cdc7-Dbf4 (Dbf4-dependent kinase; DDK) overrides replication stress in cancer cells to promote replication, which can be reversed using DDK inhibitors to promote fork stalling and cell cycle arrest." (PMID 35850776, 2022). "In particular, sorcin and DBF4 overexpression are drivers of MDR in several types of cancers; the development of inhibitors of sorcin expression and of CDC7-DBF4 activity as potential anti-tumor candidates was recently accomplished." (PMID 32268494, 2020). "To validate our findings, we conducted a study of the literature by randomly selecting five genes (DBF4, MCM2, ID3, EXOSC4, and CDKN3) from the 565 potential cancer genes." (PMID 25866773, 2015). "Using a gene effect score of <−1 as a threshold for dependency, CDT1 loss was not tolerated across most cancer cell lines whereas the consequences of CDC6 and DBF4 loss were less broad across the panel." (PMID 40460119, 2025). "Therefore, understanding the detailed structural and molecular mechanisms of Cdc7 activation by Dbf4, the docking of the DDK onto the DH, and the activation of DH by DDK would be invaluable for developing anti-cancer drugs." (PMID 35296675, 2022). "Taken together, these results suggested that β-carboline-3-carboxylic acid dimers could arrest the cell cycle by suppressing TK1, DBF4, CCNA2, CDK2, and PLK1, together with influencing some cancer-related pathways to inhibit MG-63." (PMID 36325324, 2022). "DBF4 is an important factor in cancers, although there is yet no report on its function and molecular mechanism in GC." (PMID 34758839, 2021).
tumor (15 papers, 2015 to 2025). "We utilized open-access databases like TCGA and GEO to analyze the association between DBF4 and 33 different tumor types." (PMID 38724606, 2024). "In addition, analysis of the TCGA dataset suggested that increased DBF4 expression was linked to advanced tumor T classification and shortened survival of HCC patients." (PMID 37497004, 2023). "Moreover, DBF4 has been implicated in tumor drug resistance." (PMID 38724606, 2024). "Finally, pathway inhibitor was utilized in rescue experiments to confirm whether DBF4 exerts its effects on tumor cells via the implicated pathway." (PMID 38724606, 2024). "Cdc7 and Dbf4 overexpression are reported to cause cell-cycle arrest in S phase and it has been hypothesized that increased Cdc7 activity may aid recovery or repair of stalled replication forks to enhance survival of tumor cells." (PMID 26208856, 2015). "Therefore, it can be assumed that alterations in Cdc7/Dbf4 protein activity during tumorigenesis may have important consequences for tumor cell survival, underlining the potential of Cdc7 as an anticancer target." (PMID 26208856, 2015). "Initially, we used the TCGA dataset to detect differential expression of DBF4 between various tumor types and normal tissues." (PMID 38724606, 2024). "In summary, these findings indicate that the expression of DBF4 is frequently upregulated in various tumors, indicating its potential involvement in tumor occurrence and disease progression." (PMID 38724606, 2024). "The DBF4 expression levels correlate closely with tumor size (P = 0.002), vascular invasion (P = 0.048) and TMN stage (P = 0.034)." (PMID 38724606, 2024). "To evaluate the relationship between DBF4 expression and the prognosis of tumor patients, we conducted Cox analysis on OS, DSS, PFI, and DFI using the TCGA database." (PMID 38724606, 2024). "We noted that HCC patients with DBF4 high expression had larger tumor diameter (> 5cm) and exhibited inferior survival." (PMID 37497004, 2023). "According to TCGA-BRCA data, the expression of the positive genes of risk score (HJURP, IFI27, RAD51AP1, EZH2, DNMT3B, SLC7A5, DBF4 and USP18) in tumors was higher than that in normal and tumor-adjacent tissues." (PMID 36341435, 2022). "The expression of DBF4 in tumor tissues or cells of GC was detected by qRT-PCR and western blotting." (PMID 34758839, 2021). "Statistical analysis of DBF4 expression in 32 adjacent tissues and 375 tumor tissues from TCGA showed that DBF4 was dramatically upregulated in human GC." (PMID 34758839, 2021). "Lactate in the tumor microenvironment was the primary factor that induced aberrant expression of miR-30a and DBF4." (PMID 34758839, 2021). "Together, our findings demonstrated that accumulation of lactate in the tumor microenvironment inhibited miR-30a expression and increased DBF4 expression." (PMID 34758839, 2021). "DBF4 was increased significantly in GC tumor tissues, in accordance with the results from TCGA database." (PMID 34758839, 2021). "Our findings suggest that DBF4 may regulate tumor progression by influencing the ERBB signaling pathway and its downstream pathways including JNK/STAT3, MAPK, and PI3K/AKT signaling pathways." (PMID 38724606, 2024). "It appears plausible that DBF4 drives tumor progression by modulating these key pathways." (PMID 38724606, 2024). "Since DBF4 level was found to positively correlate with tumor size, we next set out to explore whether DBF4 affected HCC growth." (PMID 37497004, 2023). "Similarly, knockdown of DBF4 in Hepa1-6 cells repressed subcutaneous and orthotopic tumor growth, decreased tumoral Ki-67 expression, and extended the mouse survival." (PMID 37497004, 2023). "Although DBF4-dependent kinase (DDK) complex composed of CDC7 kinase and its regulatory subunit DBF4 has been shown to be overexpressed in primary tumors and promotes tumor development, while its role and prognostic value in HCC remain largely unknown." (PMID 36609254, 2023).